PER3 (period circadian regulator 3)
Diseases named in the same sentence as PER3 in open-access papers (continued):
Sharing a sentence is not in itself a finding about the gene and the disease.
inflammatory bowel disease (1 paper, 2015). A spectrum of small and large bowel inflammatory diseases of unknown etiology. "Recently, another PER3 polymorphism (rs2797685) was associated with inflammatory bowel disease, a known CRC risk factor." (PMID 25501848, 2015).
internalizing disorder (1 paper, 2025). A type of mental or behavioral disorder, typically in children and young adults, with symptoms including depression, anxiety and withdrawal. "In addition, the percentage of individuals and males with an internalizing disorder significantly differed between PER3 VNTR genotypes." (PMID 41009992, 2025).
kidney cancer (1 paper, 2021). Primary or metastatic malignant neoplasm involving the kidney. "Five rhythmic genes, including PER2, DBP, PER3, CRY2, and RORA, have significant prognostic role in patient survival in at least two types of kidney cancer." (PMID 34977153, 2021).
liver cancer (1 paper, 2021). An epithelial or non-epithelial malignant neoplasm that arises from the liver. "Conversely, the expression levels of ARNTL, NR1D1, PER1, PER2, PER3, PRKAG2, and RORA were not significantly related to the OS of liver cancer patients." (PMID 34149816, 2021).
metastatic melanoma (1 paper, 2018). A melanoma that has spread from its primary site to another anatomic site. "In metastatic melanomas, male presented increased percentage of tumor showing high expression of NRD1, PER2, and PER3 (P = 0.015, P = 0.028, and P < 0.001, respectively)." (PMID 29946530, 2018).
opioid dependence (1 paper, 2021). "Importantly, circadian genes, such as Per3, which was changed in morphine-exposed male mice, have been associated with opioid-induced hyperalgesia in mice and mutations in PER3 are associated with opioid dependence in humans." (PMID 34479978, 2021).
periodontitis (1 paper, 2022). An acute or chronic inflammatory process that affects the tissues that surround and support the teeth. "Periodontitis in adults resulted in decreased levels of CSNK1D, RORA, CLOCK, DBP, NR1D1, ID2, and PER3 and a substantial increase in expression of FOS." (PMID 36472983, 2022).
placental abruption (1 paper, 2018). Vaginal bleeding preceding the 20th week of gestation. "Genetic variation in circadian rhythm genes ARNTL2, CRY2, DEC1, PER3 and RORA have also been associated with increased risk of placental abruption." (PMID 29768442, 2018).
preeclampsia (1 paper, 2022). Preeclampsia is a hypertensive disorder of pregnancy that is characterized by new-onset hypertension with proteinuria presenting after 20 weeks of gestation, and depending on mild or severe forms may initially present with severe headache, visual disturbances, and hyperreflexia. "Further, in our recent study, we found that the placenta from women with preeclampsia presented with increased CRY1 mRNA as well as reduced NR1D2 and PER3 mRNA." (PMID 36712876, 2022).
psychological distress (1 paper, 2024). "This suggests a potential association between PER3 gene polymorphism and vulnerability to psychological distress, highlighting the role of genetic factors in shaping mental health outcomes." (PMID 39759625, 2024). "Despite the observed correlations with other clinical symptoms and outcomes, such as sleep disturbances and fatigue, our findings suggest that PER3 gene variations may not directly influence psychological distress as measured by these specific psychiatric tests." (PMID 39759625, 2024).
psychosis (1 paper, 2019). "Bioinformatic analysis of WES and CGH-array data selected 15 common for psychosis phenotype damaging variants and 6 of them were rare mutations, including paternal 3p26.3-loss and 5 additional missense mutations located in ACSF2, MPRIP, PHC1, PER3, and RERE genes." (PMID 30710087, 2019).
retinal degeneration (1 paper, 2025). Degeneration of the retina. "As expected, these include clock genes such as Cry1 and Nfil3 (up) and Per3 and Nr1d2 (down) but also a few other genes, notably linked to retinal degeneration such as Myo7A61 that was substantially downregulated, or Loxl4 and Ppard that were highly upregulated." (PMID 40171795, 2025).
Sleep apnea (1 paper, 2019). An intermittent cessation of airflow at the mouth and nose during sleep is known as sleep apnea. "A recent study also demonstrated a decrease of PER3 in veterans with sleep apnea." (PMID 31590444, 2019).
sleep-wake disorder (1 paper, 2024). Abnormal sleep-wake schedule or pattern associated with the circadian rhythm which affect the length, timing, and/or rigidity of the sleep-wake cycle relative to the day-night cycle. "There were significant associations between the PER3 gene polymorphism and clinical characteristics such as sleep-wake disorder and fatigue." (PMID 39759625, 2024).
tongue cancer (1 paper, 2016). A malignant neoplasm affecting the tongue. "Of interest, the expression of key clock genes was either down-regulated, e.g., BMAL1, CLOCK, PER1, PER2, and PER3, or up-regulated, e.g. CYR1 and CRY2, in tongue cancer samples in relative to that in normal control samples." (PMID 27079271, 2016).
type 1 diabetes (1 paper, 2017). "Arntl2 is linked to type 1 diabetes and functions in T-cells, Dec2 is essential for T-cell development, and low PER3 expression is associated to several different cancers and poor prognosis." (PMID 30210560, 2017).
cancer (59 papers, 2013 to 2025). A tumor composed of atypical neoplastic, often pleomorphic cells that invade other tissues. "Mutations and copy number variations in circadian clock genes, such as ARNTL2 in colorectal cancer and NPAS2, CLOCK, and PER3 in breast cancer, are linked to cancer progression, suggesting their potential as biomarkers for cancer risk and prognosis." (PMID 39566400, 2024). "At present study, we observed multiple circadian genes, particularly PER2 and PER3, were downregulated in cancer tissue, likewise, Xiong also found that loss of PER2 expression was closely associated with the genesis and development of HNSCC37." (PMID 37968308, 2023). "Gene co-expression analysis in healthy and tumoral breast tissue samples uncovered significant associations between PER3 expression levels with those from genes which belong to several cancer-associated pathways." (PMID 34508103, 2021). "The research results demonstrated that the protein expression levels of PER1, PER2, and PER3 were significantly associated with the survival and prognosis of patients with cancer." (PMID 32849922, 2020). "A study performed in Brazilian patients with pulmonary cancer showed a strong correlation of Per3 polymorphism rs228644 and the risk of cancer (OR 1.99)." (PMID 27313610, 2016). "PER3 (period 3) is a circadian pathway gene and its variants (rs1012477, 4/5-repeat) have frequently been associated with human cancer." (PMID 25837749, 2015). "For example, there is research showing that clock gene variations, particularly to NPAS2, CLOCK, RORA, RORB, and PER3, may contribute to small but statistically significantly elevated cancer risk." (PMID 36387255, 2022). "We aimed in this article to clarify the association of PER3 variants with cancer." (PMID 25837749, 2015). "Although PER3 has tumor suppressor properties and its length polymorphism tends to have relatively penetrant phenotypic characteristics, the role of these factors in cancer susceptibility, if any, remains to be characterized." (PMID 25501848, 2015). "Studies on gene PER3 have focused on animal circadian rhythms, reproduction, gut health, and cancer." (PMID 40282783, 2025). "Emerging evidence suggests that alterations in clock genes, including the PER gene family (PER1, PER2, and PER3), play a significant role in cancer development and progression due to their regulatory functions in biological cycles and physiological processes." (PMID 38813085, 2024). "Regarding breast cancer, circadian genes like NPAS2, CLOCK, RORA, RORB, and PER3 are responsible for the formation and activation of this type of cancer." (PMID 38892035, 2024). "Recently, a colon cancer research indicated that the epigenetic regulator CBX4 was negatively associated with myeloid-derived suppressor cells and cancer-associated fibroblasts, and showed coordinated expression with PER1 and PER3 genes." (PMID 38813085, 2024). "We analyzed the difference of gene expression between normal and cancer samples, and found that the deletion of PER3 in CHOL significantly reduced the expression level." (PMID 36895015, 2023). "Gene enrichment analysis indicated that proliferation-related pathways were enriched in the PER3-low expression samples, suggesting the potential of PER3 in inhibiting cancer cell proliferation." (PMID 37342762, 2023). "Unlike the mixed roles of CLOCK and BMAL1 in CSCs, period circadian regulator genes (e.g., PER2 and PER3), generally known as tumor suppressors in various types of cancer, have been shown to inhibit CSC maintenance and survival in tumors." (PMID 36430659, 2022). "The dysfunction of PER2 and PER3 has been related to cancer development and progression as well as poor prognosis in HNSC." (PMID 36505439, 2022). "Several PER3 robust co-expression partners were also interesting given their potential implication in cancer related processes." (PMID 34508103, 2021).
cancer (continued). "Most of the genes presented positive correlations with PER3 in the healthy samples and lost this correlation in LumA cancer." (PMID 34508103, 2021). "There were 4 studies with a total of 639 cases that assessed PER2 protein expression in the prognosis of cancer and 3 studies with a total of 393 cases that assessed PER3 protein expression in the prognosis of cancer." (PMID 32849922, 2020). "There were 6 studies with a total of 427 cases that assessed PER2 mRNA expression in the prognosis of cancer and only 1 study with a total of 29 cases that assessed PER3 mRNA expression in the prognosis of cancer." (PMID 32849922, 2020). "Among these rhythm genes, PER1, PER2, PER3, and TIMELESS are the most frequently mutated genes in pan‐cancer." (PMID 31927791, 2020). "Per1, Per2 and Per3 were reported to play an important role in regulating cancer cell growth, proliferation and apoptosis." (PMID 32437452, 2020). "The core-clock genes NR1D1, PER3, CSNK2A1, and the cancer associated gene VEGFA showed statistically significant results in our Cox-regression based survival plots (log rank test p ≤ 0.05)." (PMID 32295075, 2020). "Our results showed that low Per1, Per2, Per3 and Npas2 expression played a distinct and crucial role in progression of cancers." (PMID 32437452, 2020). "PER1, PER2, and PER3 protein expression levels can be used as novel potential biomarkers for predicting cancer prognosis." (PMID 32849922, 2020). "The period genes PER1 and PER3 have been found to suppress cancer cell growth and have also been observed to be deregulated in breast cancer." (PMID 31949161, 2020). "Decreased expression through hypermethylation of CpG islands or aberrant acetylation in the promoters of the core circadian genes Per1, Per2, and Per3 are reported in a spectrum of human cancers." (PMID 31409384, 2019). "The alteration frequencies of core clock genes were lower than 5% in most cancers, with the exception of PER3 in CHOL and CLOCK in LUSC." (PMID 30791227, 2019). "For instance, PER1 was deleted in 16 cancers, while PER3 and CLOCK were lost in 15 and 12 cancers respectively." (PMID 31014368, 2019). "We showed that PER1, PER2, and PER3 gene expression levels were all lower in cancer tissue than in liver tissue, while CSNK1E gene expression was higher in cancer tissue." (PMID 27492458, 2016). "It has been demonstrated that per3 is involved in multiple processes such as circadian rhythm, sleep, cancer, cell proliferation and apotosis." (PMID 24024969, 2013). "Studies suggested that the expression of PER3 may be altered in certain cancers; however, the precise role of PER3 in cancer development is not known." (PMID 40534841, 2025). "The study found that PER3 was overexpressed in 22 out of 33 common human cancers." (PMID 39771050, 2024). "PER3 expression was analyzed in 33 cancer datasets from the TCGA database." (PMID 39771050, 2024). "Collectively, these studies suggest that PER2 and PER3 are negative regulators of CSC physiology that could be potential targets for anti-CSC cancer therapy." (PMID 36430659, 2022). "The prognostic relevance of PER3 function in cancer cell stemness is further indicated by a study showing that patients with high levels of PER3 expression have better survival rates than those with low levels of PER3 expression." (PMID 36430659, 2022). "Furthermore, these Per3-low cancers are more aggressive, and the patients have a shorter relapse-free survival compared to patients with wild-type Per3." (PMID 34958429, 2021). "The top intracellular pathways of the 12 overlapping genes were associated with circadian rhythms and entrainment (Arntl, Cry2, Per2, Per3, Bhlhe41), the cell cycle (Cdkn1a, Wee1), the oxytocin signaling pathway (Cdkn1a, Rcan1), and transcriptional misregulation in cancer (Cdkn1a, Per2)." (PMID 33668521, 2021). "The association between PER1 and PER3 mRNA expression levels and cancer prognosis was not meta-analyzed as the number of experimental studies was <3." (PMID 32849922, 2020).
cancer (continued). "Furthermore, hypermethylation of PER1/PER2/PER3 was observed in most cancers, although the hypermethylation of PER3 was only statistically significant in HNSC, BRCA, and THCA." (PMID 30791227, 2019). "Their functional effects on cancer prognosis could also be of interest since both PER1 and PER3 belong to core circadian genes, which are involved in cancer development and progression." (PMID 26927666, 2016). "This study demonstrates that the down-regulation of PER1 in cancer cells can result in the robust up-regulation of PER3, TIM, RORα and REV-ERBα transcripts, while the expression of PER2, DEC1, DEC2, CRY1, CRY2 and NPAS2 is prominently down-regulated in vitro and in vivo." (PMID 27602964, 2016). "In summary, our meta-analysis, on the basis of statistical data, suggested no relevance of common variants in PER3 to cancer susceptibility." (PMID 25837749, 2015). "Cancer of prostate, breast, and colorectal was studied in the publications of PER3 4/5-repeat." (PMID 25837749, 2015). "Few studies have examined the role of the PER3 VNTR on cancer-related outcomes." (PMID 25501848, 2015). "Besides, altered PER3 expression has been reported in various cancers, including CML, HNSCC, HCC, and CRC." (PMID 24708606, 2014). "Besides the PER3VNTR and cancer associations framed inside LAN hypothesis another avenues of association between cancer and PER3 have been explored." (PMID 34508103, 2021). "However, our co-expression analysis suggests that PER3 could be involved in several molecular mechanisms related to cancer which include energy metabolism, signaling through cancer related pathways such insulin and PI3K/AKT signaling and cell cycle control." (PMID 34508103, 2021). "The intersection of differentially expressed genes (DEG) and our list of candidate genes, resulted in 12 elements including cancer associated genes (NRAS, MYC, and VEGFA), circadian drug targets (SOD2 and CES2) and core-clock and ECCN genes (AHR, CREB1, CSNK2A1, NFIL, NPAS2, NR1D1, and PER3)." (PMID 32295075, 2020). "Therefore, although heterogeneity existed, these pooled results suggested that low expressions of Per1, Per2, Per3 and Npas2 might play important roles in the development and progression of cancers." (PMID 32437452, 2020). "For instance, CLOCK was selectively expressed in ER+ cancer, whereas PER1 and TEF were highly expressed in both ER+ and HER+, and finally PER3 was expressed in HER2+ and TNBC." (PMID 39201344, 2024). "While many cancer cell types continue to exhibit oscillations of the circadian clock, it was shown that deregulation of the key clock genes PER1, PER2, PER3, CRY1, CRY2, BMAL1, and CLOCK occurs in certain human malignancies." (PMID 38892035, 2024). "GEPIA was used to understand the messenger (m)RNA expressions of circadian rhythm-related factors in the PER family (PER1, PER2, and PER3), CRY family (CRY1 and CRY2), BMAL1, and CLOCK in different types of cancer." (PMID 36385012, 2022). "On the contrary, the expression of PER2, PER3, CRY1, KIAA1737, and BHLHE41 are negatively correlated with the infiltration level of four tumor‐infiltrating lymphocytes in pan‐cancer." (PMID 31927791, 2020). "Among 716 samples across 29 cancer types, we interestingly observe that most of the negative regulators, such as PER1, PER2, PER3, CRY1, CRY2, and NR1D2, are down-regulated in a wide range of cancers." (PMID 31708917, 2019). "proved that promoters of these clock genes (PER1, PER2, PER3, CRY1 and CRY2) were methylated in a variety of cancer cells, which resulted in their decreased expression." (PMID 27602964, 2016). "We demonstrated that in vitro and in vivo cancer cells after PER1 knockdown, PER2, DEC1, DEC2, CRY1, CRY2 and NPAS2 were significantly down-regulated at the mRNA level, while PER3, TIM, RORα and REV-ERBα were significantly up-regulated." (PMID 27602964, 2016).
cancer (continued). "Meanwhile, others clock genes were downregulated including PER1 in 11 cancer types, PER2 in 7, PER3 and CRY2 in 10 and RORα in 11, indicating they may act as tumor suppressor genes." (PMID 33042011, 2020). "PER3 was absent in nucleus of normal mucosa, but expressed in cancer cells and their neighbouring mucosa." (PMID 27465361, 2016). "Quantitative real-time PCR result indicated that in vitro and in vivo cancer cells after PER1 knockdown, PER2, DEC1, DEC2, CRY1, CRY2 and NPAS2 were significantly down-regulated at the mRNA level, while PER3, TIM, RORα and REV-ERBα were significantly up-regulated." (PMID 27602964, 2016). "Three eligible studies of PER3 4/5-repeat yielded a total of 2492 cancer patients and 2749 noncancerous controls." (PMID 25837749, 2015). "In order to achieve a systematic understanding of circadian clock in cancer, we define a core subset of clock family genes including 7 positive regulators (CLOCK, NPAS2, ARNTL, ARNTL2, RORA, RORB, and RORC) and 7 negative regulators (PER1, PER2, PER3, CRY1, CRY2, NR1D1, and NR1D2)." (PMID 31708917, 2019). "For instance, CLOCK and PER3 were preferentially expressed in tumour and stomal cells, while PER1 was selectively expressed in immune cells and stromal cells but not in cancer cells." (PMID 39201344, 2024). "When cells from the same dataset were stratified based on cellular type, CLOCK and PER3 were preferentially expressed in tumour and stomal cells, PER1 was selectively expressed in immune cells and stromal cells but not in cancer cells, and TEF was selectively expressed in CAF subtypes." (PMID 39201344, 2024).